CD69 (CD69 molecule)
Diseases named in the same sentence as CD69 in open-access papers (continued):
Sharing a sentence is not in itself a finding about the gene and the disease.
tumor (continued). "In contrast, SX-682 affects tumor growth and produces a more anti-tumor immune environment characterized by increased CD8+ T cells and activated CD69+CD8+ T cells." (PMID 40904502, 2025). "Treatment with anti‐PD‐1 and anti‐CTLA‐4 therapy led to the expansion of intratumoral CD69+CD103+CD8+ TRM cells, significantly increasing their cytotoxic capacity in TNBC patients and providing local immune protection against tumor rechallenge." (PMID 39802636, 2025). "Mechanistically, NeoViron enhanced the cytotoxicity of CD8+ T cells and promoted the expansion of CD69+ CD8+ tissue-resident memory T cells and TCF1+ CD8+ stem-like T cells to promote anti-tumor immunity and immune memory." (PMID 41429778, 2025). "CAR T cells at the tumor site were isolated and analyzed by flow cytometry; the data showed that IL15C-NKG2D-CAR T cells expressed higher levels of cytokines CD69, CD107, and GzmB at the tumor site." (PMID 40625735, 2025). "This is further complicated by the fact that tumor infiltrating CD8+ Trm are generally monitored using phenotypic markers, most commonly cell surface co-expression of CD69 and the CD103 or CD49a integrins, as used in this study." (PMID 40162209, 2025). "The tSNE plot shows an increase in the frequency of CD3+, CD4+ and CD8+T cells, CD69, PD1 and PD-L1 expression on T cells, and a decrease in the frequency of epithelial cells after treatment, indicating enhanced anti-tumor immune responses." (PMID 38516270, 2024). "Peripheral tissue-resident memory T cells evidenced by markers such as CD103, CD69 and CXCR6 elicited a robust cellular immunity by recruiting and activating cytotoxic CD8 T cells and NK cells in a PD-L1 blockade treatment tumor mouse model." (PMID 39076974, 2024). "We have assessed the overall level of tumor-infiltrating leukocytes (CD45+) and the level of “exhausted” CD8+ T cells expressing PD-1 inhibitory receptors as well as activation marker CD69 within the TME following applied treatment." (PMID 38832958, 2024). "NK cells were activated in the course of tumor growth in both RMA and RMA-KR models, as demonstrated by coordinated up-regulation of CD69 and Ki67." (PMID 39196934, 2024). "In AKR tumor samples, we also observed increased proportion of activated CD8+ T population (CD69 and IFNγ) in Trp63-knockdown tumors." (PMID 38509096, 2024). "In vitro results showed increased IFN-γ secretion, CD69, and CD25 expression upon co-culturing with HLA-G12V/CD3 BiTE and tumor cells." (PMID 38752985, 2024). "Our observations revealed a significant increase in CD25, CD69, and CD62L expression in LPS-RGD-Nb36-DOX as well as DC/tumor fusion vaccine-activated CD8+ T cells (P < 0.001)." (PMID 38824143, 2024). "This increase in the frequency of CD8+PD1+, CD8+CD69+ and granzymeB+CD8+T cells was also observed in livers of mice with low KPN metastatic tumor burden (Fig-S5A-5D)." (PMID 38516270, 2024). "VSV-p15 also significantly increased NK cell tumor infiltration, and both VSV-p14 and VSV-p15 increased NK cell CD69 expression, demonstrating increased activation by VSV expressing FAST proteins." (PMID 38750591, 2024). "An improved tumor inhibition, an increased TIL infiltration and expression of granzyme B, perforin, as well as CD69 were found in mice treated with PHD2/3 KO CD8 T cells, when analyzed 7 days after ACT." (PMID 39242595, 2024). "Upon co-incubation with CD19-expressing tumor cells, the activation of NFκB and NFAT, the upregulation of CD69, CD25 and 4-1BB, and the secretion of IFNγ and TNF were severely impaired by the phospho-mimicking CAR variants compared to the WT CAR." (PMID 38779683, 2024). "To validate our findings, we examined the expression of activation (CD69, OX40) and exhaustion markers (LAG3, TIM3) markers on T cells in FFPE tissue sections from humanized EMC041 PDX tumours collected at sacrifice." (PMID 38711203, 2024).
tumor (continued). "While both CD69 and CD103 are established markers of TRMs, we focused on CD103 because it is a more stable and specific marker of long-term tissue residence in tumor tissues." (PMID 39594720, 2024). "Immunofluorescence (IF) staining demonstrated that treatment with BAPN or LOX-neutralizing antibodies in tumor-bearing C57BL/6J mice increased intratumoral CD8+ T cells and activated CD8+ (CD8+CD69+) T cells." (PMID 39352749, 2024). "Treatment with rNDVs led to an increase in the size of tumor-draining LNs and a sizeable increase in the percentage of CD69 and CD25 activated CD8+ cytotoxic T cells was detected in inguinal tumor-draining LNs after treatments with any of the three rNDVs." (PMID 38328418, 2024). "After treatment, the TCRbhiPD‐1hiCD69+CD27+ CD8+ Teff decreased in proportion in the HB group, while the proportion of Ly6ChiTCRb+CD69+CD27+CD62L+ CD8+ Tcm increased, underscoring the enhanced ability of the immune system to effectively eradicate tumor cells." (PMID 39135526, 2024). "Similar to scRNA-Seq data, the FACS analysis also revealed that tumor-infiltrating TCR135-T cells had increased levels of exhaustion markers (TIM3 and PD-1) and tissue-resident memory markers (CD69 and CD103)." (PMID 38412034, 2024). "The number of tumor-specific CD8+ CTLs in the draining lymph nodes was higher than that in the control group; moreover, the proportions of CD69+CD8+ CTLs and CD107a+CD8+ CTLs with toxic functions were increased." (PMID 38261253, 2024). "Conversely, C11, featured by Ly6ChiTCRb+CD69+CD27+CD62L+, represented a subset of CD8+ Tcm lymphocytes with potential tumor‐killing characteristics." (PMID 39135526, 2024). "Despite detecting an increase in T effector cells expressing markers of early (CD69) and late (CD25) activation, it was important to confirm that these cells were tumor-specific." (PMID 38328418, 2024). "GrB+ B cells from tumor samples exhibited slightly higher expression levels of LAIR1 and NR4A1 but a lower level of CD69 expression." (PMID 38386050, 2024). "The serum copper level significantly correlated with the percentage of CD3+CD69+, CD4+PD-1 and CD8+PD-1 in tumor samples and CD4+PD-1, CD8+PD-1 in node samples." (PMID 38256645, 2024). "The activation state of expanded Vδ2+ T cells via CD25, CD69 and CD137 was also assessed in cocultures with WiDr, WM9 and HAP1 tumor cells." (PMID 38426099, 2024). "We have shown that iron levels significantly positively correlated only with the expression of CD4+ CD69+ lymphocytes T (p = 0.014) and CD4+ CD25+ T lymphocytes (p = 0.023) in tumor samples and CD3+ CD25+ T lymphocytes (p = 0.018) in node samples." (PMID 38256645, 2024). "Using in vivo imaging techniques in mouse melanoma models, they found that many tumor-specific epidermal CD69+ CD103+ TRM T cells increased over time and gradually killed the tumor cells." (PMID 38534538, 2024). "Statistically significant differences were seen between zinc and CD19+CD69+ tumor, CD4+CD25+ node T lymphocytes and Cu and: CD3+CD69+, CD4+PD-1, CD8+PD-1 tumor, and CD4+PD-1, CD8+PD-1 node T lymphocytes." (PMID 38256645, 2024). "Consistently, OT-I T cells co-cultured with thimerosal-treated tumor cells also upregulated the expression levels of activation markers CD25, CD69, and effector molecules such as intracellular Granzyme B (GZMB) and IFNγ." (PMID 39349845, 2024). "This population of CD8+ T cells comprises cells exhibiting CD69+ activation markers and recognizing both VACV A5275-83 and tumor p66 HER/neu epitopes." (PMID 38498459, 2024). "While both Li and Mi exercise normalized the tumor vasculature, only Mi exercise increased tumor infiltrated CD8+ T cells, that also displayed enhanced effector function (higher proliferation and expression of CD69, INFγ, GzmB)." (PMID 38495879, 2024).
tumor (continued). "An upregulation of GZMB expression in tumor-infiltrating CD8+ T cells was detected in tumors treated with Z36-MP5, as well as the activation markers CD69, IFN-γ, CD25 and CD107, whose expression was augmented by combinatorial treatment with anti-PD-1." (PMID 38461299, 2024). "Statistically significant differences were seen between iron and CD4+CD3+ T lymphocytes; CD4/CD8 ratio; CD4+CD69+ tumor; CD4+CD25+ tumor; CD8+PD-1 tumor; CD3+CD25+ node T lymphocytes; and CD19+PD-1 node B lymphocytes." (PMID 38256645, 2024). "Following coculture with CD33+ tumor cells, both CAR33 and DARIC33 T cells exhibited a similar activation profile; however, the CAR33 cells had higher expression of PD-1, LAG3, CD69, and CD25, suggesting greater activation following T cell activation." (PMID 38502193, 2024). "We detected TRM-like (CD69+CD103+) CD8+ T cells in tumour-bearing HIS mice and found a significantly higher abundance in tumour compared with spleen (p = 0.0022, paired t-test)." (PMID 38986249, 2024). "A statistically significantly higher level of activated CD8+ T cells via CD69+ and CD25+ expression was noted in the TILT-322 virus-treated group compared to Ad5/3-E2F-d24-aMUC1aCD3 + T cell, backbone + T cell and tumor + T cell groups." (PMID 38910324, 2024). "Within the tumor antigen specific CD8+ T cells, the percentage of CD39 and CD69 double positive cells varies greatly between patients." (PMID 37359554, 2023). "Lastly, we confirmed the specificity of the TILs to the highest responding tumor antigens, and identified this reactivity resides largely in CD39+CD69+ terminally differentiated populations." (PMID 37359554, 2023). "In the tumor-draining lymph nodes, CD4+ T cell depletion or its combination with PD-L1 blockade therapy significantly elevated the proportions of CD44+CD69+CD8+, as well as central memory CD44+CD62L+CD8+ and effector memory CD44+CD62L−CD8+ T cells." (PMID 36969495, 2023). "We observed that in the course of tumor progression that the proportion of both the antigen specific tetramer positive population and the SLAMF6+CD69+ progenitor population were progressively diminished." (PMID 37914685, 2023). "When compared to both the control group and the LiSmore group without photostimulation, the LiSmore group displayed 2-4 fold increase in CD69, Ki67, and IFN-γ staining following light treatment in the tumor sites." (PMID 37673917, 2023). "IF staining of tumor and spleen tissues from ICI-treated animals demonstrated the expression of CD69 on T cells via the coexpression of CD69 and CD3, putatively representing activated T cells (respectively)." (PMID 37426447, 2023). "It was also shown that the majority of infiltrating CTLs in tumor beds exhibited effector (CD8+CD28+), memory (CD45RO+), or activated phenotype (CD25+, CD69+, HLA-DR+) and the naive subset (expressing CD45RA and CCR7) compromised the least proportion." (PMID 37835465, 2023). "Tumour-infiltrating and circulating T cells had significantly lower CD27 expression and significantly higher CD69 expression post-FLOT and post-CROSS treatment." (PMID 35986757, 2023). "Co-expression analysis of paired PBMC and tumor periphery samples using flow cytometry showed that CD69+ CD103- and CD69+ CD103+ cells are the dominant CD8+ T cell populations in the tumor periphery." (PMID 38127790, 2023). "The V9302 in this nanosystem inhibited glutamine uptakeof tumor cells and increased the glutamine level within the TME, thusimproving tumor infiltration of CD8+ Teff cells and theproportion of intratumoral activated T cells (CD69+ andCD25+)." (PMID 37901179, 2023). "The expression of NK cell receptors, such as the Fc gamma receptor CD16, the C-type lectin receptor CD94 and the activation markers CD69, NKp30, NKp46 and NKG2D, were measured to investigate their anti-tumor potential." (PMID 37238744, 2023).
tumor (continued). "CD69+ activated CD8+ T cells are significantly reduced in diethylnitrosamine induced HCC models and participate in tumor evasion of immune responses." (PMID 37156819, 2023). "We also verified this phenomenon from co-culture experiments, in which overexpression of ICAM1 on cancer cells enhanced CD69 and PD-1 expression on CD8+ T cells after their direct contact with tumor cells for 24 h." (PMID 36871040, 2023). "By examining the levels of effector molecules (CD69, CD107a, GZMA, IFN-γ, TNF-α, GZMB, and Perforin-1), we also noticed that the tumor-infiltrating CD8+ T cell effector response was significantly enhanced by Rig-I deficiency." (PMID 36927693, 2023). "We found that the mRNA expression CD68, CD69 and CYP27A1 levels were significantly downregulated, and PLTP levels was significantly up regulated in tumor samples." (PMID 37880277, 2023). "Over the course of MC38 tumour progression, there was a significant increase in CD8+ TILs expressing CD69 (15→86%), with these cells also co-expressing PD-1 (data not shown)." (PMID 37153625, 2023). "We also found that PSGL-1 blockade resulted in a 1.6-fold higher frequency of tumor-infiltrating CD3+ cells and 30% higher expression of CD69 on intratumoral CD8+ T cells, indicating increased activation of these cells." (PMID 37819238, 2023). "CD69+ expression was significantly increased on CD8+ and CD4+ T cells both within the tumor and spleen." (PMID 37426447, 2023). "Flow cytometry analysis of tumor-bearing BM revealed a significant increase in CD4+ and CD8+ T-cell activation at day 7 in treated versus control as revealed by CD69 staining." (PMID 36968140, 2023). "Following tumor recognition, T cells showed increased expression of activation markers (CD137, CD69, IL-2, and TNF-α)." (PMID 37683639, 2023). "Lenti‐HPV‐07 therapy also showed its full efficacy in a lung metastatic tumor model, correlated with the presence of CD44+ CD69+ CD103+ CXCR3+ resident memory CD8+ T cells in the lung parenchyma." (PMID 37675835, 2023). "Similar findings were observed in the tumour tissue, wherein post-CROSS CRT the percentages of tumour-infiltrating CD3+CD8+CD69+ T cells were significantly higher compared with treatment-naïve tumour tissue (63.3 ± 10.0 vs. 90.08 ± 3.0%, p = 0.04)." (PMID 35986757, 2023). "Significance testing based on differential gene expression analysis shown in panel (E) Representative dot plots of CD69 and CD103 co-expression in CD8+ T cells from PBMC and tumor-periphery." (PMID 38127790, 2023). "The expressions of CD44 and CD69 and those of granzyme B (GrB) and IFN-γ, which is involved in tumor eradication, were analyzed by flow cytometry." (PMID 37875555, 2023). "Meanwhile, the numbers of CD8+ T cells, proliferated CD8+ T cells, and activated CD8+CD69+ T cells, CD8+IFNγ+ T cells and CD8+GzmB+ T cells were the highest in tumor tissues of R848@M2pep-MPsAFP and anti-PD-1 antibody-treated group." (PMID 37704614, 2023). "When the CD69+CD8+ TRM cells and tumor cells were transplanted into naïve mice i.c., the αCD69 antibody treatment did not disrupt the antitumor efficacy of CD8+ TRM cells." (PMID 36759517, 2023). "Overall, we observed that PBMCs activated in the presence of conditioned media generated from OGJ patient-derived tumour biopsies at time-points post-FLOT and post-CROSS CRT treatment decreased CD27 and increased CD69 expression." (PMID 35986757, 2023). "Thus, CD69 may have a double-edged sword effect on tumor immunity." (PMID 37880277, 2023). "The populations of CD3+ tumor-infiltrating T lymphocytes (TILs), Teffs (CD8+), and activated Teffs (CD8+CD69+) in primary and distant tumors of HPNP-injected mice were higher than that of proteins-, HNP-, or PNP-injected mice after sono-irradiation." (PMID 35710545, 2022). "We observed significantly higher levels of exhaustion (ICOS, TIM3, CTLA4, PD1, LAG3, TIGIT) and activation (TNFSR9, CD69, CD25) markers for clonotypes restricted to the tumor." (PMID 36185254, 2022).
tumor (continued). "Results of data mining transcriptomes and clinical files from a large cohort of GBM samples revealed that the cumulative survival was higher in GBM patients with a high number of tumor-infiltrating CD8+ T cells and ITGAE (CD103) and CD69 positive cells." (PMID 36289717, 2022). "The intensity and distribution of CD69+, CD28+, and CD103+ expression on CD8+ T cells were all increased in the LAIT‐treated tumours." (PMID 35808806, 2022). "The combination treatment enhanced the expression of CD69 in the tumor-infiltrating CD8+ T cells, increased tumoral GzmB, and decreased tumor cell proliferation." (PMID 35380995, 2022). "While CD69, CD103 and CD49a have been used to discriminate TRM from other memory subsets, CD39 has recently been described as a distinguishing marker of tumor specific CD8 TILs." (PMID 36466880, 2022). "There was also a large reduction in the proportion of CD28+CD69– cells (black clusters, red arrows) and an increase in the CD28+CD69+ cells (red dots) in the LAIT‐treated tumours, suggesting the differentiation and activation of CD8+ T cells following LAIT." (PMID 35808806, 2022). "The numbers and the levels of CD69, IFN-γ, and GZMB in tumor-infiltrating CD8+ T cells were increased in sgRad21 ID8Trp53–/– tumors compared with scramble sgRNA–carrying tumors." (PMID 36201246, 2022). "Subclusters with Entpd1 expression were assigned as tumor-specific T cells, including Treg (CD4+Foxp3+), CD8+ effector (Gzmb+Prf1+Ifng+), CD8+ effector memory (Cd44+Cd69+), CD8+ exhausted subclusters (Pdcd1+Lag3+Tigit+Havcr2+)." (PMID 36209176, 2022). "T cells isolated from HT-29 tumours 24 h after the last dose of injection with VV-αCEA TCE and PBMCs showed an increase in expression of the T cell activation marker CD69, while injection of VV-αCEA CTRL had little effect relative to PBS treatment." (PMID 36405739, 2022). "Some reports suggest that in the presence of EGFR ligand secreted by tumor cells, CD3+CD8+CD69+Ki67+ T-lymphocytes produce more IFN-γ and TNF-α and show a stronger antitumor response." (PMID 36142766, 2022). "The expression of CCL20, CD70, PCDH7, DCBLD2, and MMP14 genes were remarkably more elevated within LUAD samples than adjacent non-tumorous tissues, where PIK3R5, RNF144B, BTG2, CD69, and MEP1A genes were the opposite." (PMID 36497225, 2022). "Consistent with this, the prevalence of CD69- and IFN-γ-producing CMVp-CTLs among the tumor-infiltrating cells was substantially higher after treatment with either inCT†CMVp480–503 or inCT†CMVp480–516 than after treatment with the control substances." (PMID 35459256, 2022). "In our study, we not only found a higher percentage of CD69+ and CD25+ T cells in the blood samples as compared to healthy controls, but we also observed an increase in these lymphocytes in the tumor samples as compared to the lymph node samples." (PMID 35158748, 2022). "A B-cell subset expressing activation markers (CD25+CD69+B7-H1+CD81+CD86+) and termed tumour-evoked Bregs (tBreg) induced the generation of Foxp3+Tregs, which inhibited anti-tumour responses." (PMID 35350071, 2022). "Activation markers CD25 and CD69 were downregulated after NECA treatment and AB928 reversed this effect, both for cocultures with antigen expressing tumour cells or recombinant EpCAM stimulation." (PMID 36266575, 2022). "The levels of T cell activation markers CD69, IFN-γ, and GZMB in tumor-infiltrating CD8+ T cells were increased in sgRad21 B16-OVA tumors compared with scramble sgRNA–carrying tumors." (PMID 36201246, 2022). "Differential analysis showed that GNAI3, PCDH7, PSEN1 and TNFSF9 were highly expressed in tumor tissues, while ADM, CD69, SLC11A2 and TLR2 were opposite." (PMID 36117156, 2022). "The expression of the early activation marker CD69, which also controls the exhaustion of effector cells, progressively increased with advancing UICC tumor stages." (PMID 36428793, 2022).